MIR103A2 (microRNA 103a-2)
Synonyms: hsa-mir-103-2; hsa-mir-103a-2; MIR103-2; MIRN103-2; mir-103a-2
Gene: MicroRNA gene on chromosome 20 (3,917,494 to 3,917,571, forward strand). Ensembl gene ENSG00000199024.
Gene Ontology:
Biological process: miRNA-mediated post-transcriptional gene silencing
Cellular component: RISC complex
Homologues: Orthologues: chimpanzee ptr-mir-103-2 (100% identical), guinea pig MIR103A2 (100% identical), macaque mml-mir-103-2 (100% identical), mouse Mir103-2 (99% identical), pig ssc-mir-103-2 (99% identical), rabbit MIR103A2 (99% identical), rat Mir103a2 (99% identical), dog MIR103-2 (96% identical), tropical clawed frog xtr-mir-103-2 (90% identical), zebrafish dre-mir-107 (82% identical), zebrafish dre-mir-103 (81% identical), zebrafish mir107b (69% identical). Paralogues in human: MIR107 (86% identical), MIR103A1 (81% identical).